TIMP1 (TIMP metallopeptidase inhibitor 1)
Diseases named in the same sentence as TIMP1 in open-access papers (continued):
Sharing a sentence is not in itself a finding about the gene and the disease.
liver fibrosis (continued). "We further demonstrated that miR-6676-3p downregulated the mRNA expression of α-SMA, COLLAGEN I, TIMP1, TIMP3 and upregulated MMP2, MMP9, which are all profibrogenic genes in which TIMP1/3 antagonize MMP2/9 which decompose the collagen I during the progression of liver fibrosis." (PMID 34930304, 2021). "In addition, the expression of tissue inhibitor of matrix metalloproteinase 1 (TIMP-1) is increased in human and rat models of liver fibrosis, and its degree of expression correlates with the extent of fibrosis in human liver." (PMID 34557535, 2021). "However, Mmp3 and Timp1 genes, whose impact on liver fibrosis is controversial or unclear, were strongly induced in wildtype mice livers but showed significantly lower or negligible induction in NLRC5-deficient livers." (PMID 34712238, 2021). "The molecules, including Scd1, Acta2, collagen type I alpha 1 chain (Col1a1), Timp1, Foxm1, Sult1e1, and plasminogen activator (Plat), are also involved in hepatotoxicity pathways, such as liver fibrosis, liver hyperplasia/hyperproliferation, liver proliferation, and liver necrosis/cell death." (PMID 34539442, 2021). "The purpose of this study was to investigate if Hyaluronic Acid (HA), TIMP metallopeptidase inhibitor 1 (TIMP1), Amino-terminal Propeptide of Type-III Collagen (PIIINP) and Enhanced Liver Fibrosis (ELF) score associate with histological liver disease in neonatal baboons exposed to PN." (PMID 32150543, 2020). "Similarly, the mRNA levels of PLK1 and fibrogenic genes (α‐SMA, Col1α1 and TIMP‐1) were higher in liver fibrosis than in healthy livers, as shown by real‐time PCR." (PMID 32463161, 2020). "TIMP1 is used, in conjunction with 2 other proteins, in the Enhanced Liver Fibrosis test (ELFTM; Siemens Healthineers), which determines a patient’s risk for liver fibrosis." (PMID 33119677, 2020). "For liver fibrosis in rats induced by CCl4, ginseng extract inhibits liver inflammation by downregulating rat hepatic prostaglandin E2 and tissue inhibitor metalloproteinase-1 (TIMP-1)." (PMID 32724321, 2020). "YAP is expressed in hepatocytes and activates the expression of proteins that promote fibrosis (ColL1α1, TIMP1, TGFβ2) and inflammation (TNFα, IL-1β), which stimulate the expansion of myofibroblasts and the recruitment of immune cells, exacerbating liver fibrosis." (PMID 32660130, 2020). "Four TIMPs (TIMP-1, TIMP-2, TIMP-3, and TIMP-4) are known to be associated with liver fibrosis." (PMID 32664553, 2020). "Furthermore, elevated TIMP1 has also been shown to correlate with hepatic fibrosis in cystic fibrosis liver disease." (PMID 32150543, 2020). "Furthermore, both TIMP1 and SLPI are induced by IL-6 as shown by studies on the pathogenesis of liver fibrosis and inflammation caused by innate immunity." (PMID 31404090, 2019). "MMP-13 and TIMP-1 play a crucial role in modulation of liver fibrosis in rodents." (PMID 31118972, 2019). "Since we show that external rigidity alone affects MMP-9 and TIMP-1 activity, we demonstrate the importance of mechanotransduction of high rigidities in liver fibrosis, in concurrence with studies that link the rigidity of the fibrotic liver to disease progression." (PMID 31086224, 2019). "However, tissue inhibitor of metalloproteinases-1 (TIMP-1), a surrogate marker for liver fibrosis, was comparable in the serum of LCMV-infected and uninfected BDL animals." (PMID 30111770, 2018). "The enhanced liver fibrosis (ELF) score was calculated from the TIMP-1, PIIINP, and HA values." (PMID 30547825, 2018). "To test the hypothesis that TIMP-1 is in fact functionally relevant for the development of liver fibrosis we subjected wild type and TIMP-1 ko mice to two different models of liver fibrosis." (PMID 28386095, 2017). "Furthermore, secretion of TIMP-1 is involved in spontaneous resolution of liver fibrosis by the combination of a net reduction and suppression of apoptosis; conversely, downregulation of TIMP-1 has been found to exacerbate liver injury and fibrosis." (PMID 28360865, 2017).
liver fibrosis (continued). "Unexpectedly, in comparison to wild type littermates, TIMP-1-deficient mice were not protected from liver fibrosis induced by BDL or CCl4." (PMID 28386095, 2017). "Furthermore, studies suggest that antibody and antisense oligonucleotides directed to TIMP-1 attenuate rat liver fibrosis." (PMID 27776513, 2016). "Using the carbon tetrachloride (CCl4) preclinical model of liver fibrosis in mice, we observed a significant increase in collagen deposition with increased expression and release of tissue inhibitors of metalloproteinase (TIMP)-1 both at 24 h and 3 weeks later." (PMID 27247426, 2016). "TIMP-1 over-expression may exacerbate liver fibrosis, and hepatic fibrosis may mediate fibrosis through the TIMP-1 dependent signalling pathway." (PMID 27247426, 2016). "Thus, the primary aim of our study was to determine the reliability of serum samples of HCV-infected patients cryopreserved over a long period of time to assess significant fibrosis using HA, PIIINP, TIMP-1 and the Enhanced Liver Fibrosis (ELF®) score." (PMID 27984583, 2016). "TIMP-1 is a critical factor regarded to fibrogenesis and can prohibit the degradation of the extracellular matrix, and its expression leads to the deposition of extracellular matrix in models of liver fibrosis." (PMID 26075890, 2015). "Both MMP2 and TIMP1 regulate the process of liver fibrosis via TGF-β1 mediation." (PMID 26378522, 2015). "Additionally, in studies of liver fibrosis, a correlation has been seen between the levels of TIMP-1 and Bcl-2." (PMID 26366732, 2015). "These roles during chemical injury do not appear to apply during Th2-mediated injury because deficiency of TIMP-1 or TIMP-2 does not seem to affect liver fibrosis in response to S. mansoni infection." (PMID 24713275, 2014). "Likewise, TIMP-1 strongly promotes liver fibrosis development in CCL4-treated TIMP-1 transgenic mice." (PMID 25549087, 2014). "Particularly, MMP2 and TIMP1 are expressed primarily in liver fibrosis." (PMID 24860243, 2014). "On the other hand, in pediatric patients TIMP-1 could be clinically useful for predicting liver fibrosis in patients with CHC." (PMID 23326448, 2013). "Moreover, antagonization of TIMP-1 by a catalytically inactive mutant MMP-9 or by TIMP-1 neutralizing antibody decreases liver fibrosis." (PMID 23755201, 2013). "TIMP-1 serum concentration levels have been examined in patients suffering from several types of cancer such as colorectal cancer and lung cancer, and also in terms of acute disseminated encephalitis or liver fibrosis." (PMID 22547904, 2012). "Acceleration of liver fibrosis by increased liver injury in TIMP-1-/- mice may dominate over the profibrogenic effect of TIMP-1 on liver fibrosis, leading to greater liver fibrosis in TIMP-1-/- mice after CCl4 treatment." (PMID 21711826, 2011). "Although it has been reported that TIMP-1 plays an important role in liver fibrosis and regeneration, its function during hepatocellular injury remains unclear." (PMID 21711826, 2011). "In addition, TIMP-1 also plays an important role in promoting liver fibrosis but inhibiting liver regeneration." (PMID 21711826, 2011). "Deletion of TIMP-1 may reduce liver fibrosis through abolishing the profibrogenic effect of TIMP-1, but may also accelerate liver fibrosis by increasing liver injury." (PMID 21711826, 2011). "In addition, transgenic mice overexpressing human TIMP-1 developed more liver fibrosis when subjected to chronic CCl4 administration, and demonstrated attenuated spontaneous fibrosis resolution." (PMID 20593020, 2010). "Additionally, TCSO markedly downregulated the expression of key fibrogenic proteins, such as transforming growth factor-β1 (TGF-β1), matrix metalloproteinase-2 (MMP-2), and tissue inhibitor of metalloproteinases-1 (TIMP-1), thereby effectively suppressing the progression of hepatic fibrosis." (PMID 41823869, 2026).
liver fibrosis (continued). "In the context of liver diseases, OSM enhances the expression of tissue inhibitor of metalloproteinases 1 (TIMP1), suppresses fibrinolytic activity in hepatic stellate cells, and facilitates the proliferation of myofibroblasts, thereby contributing to the pathogenesis of liver fibrosis." (PMID 40969371, 2025). "In contrast, another study in TIMP-1-deficient mice could not confirm the role of TIMP-1 in liver fibrosis." (PMID 39201329, 2024). "Moreover, TIMP-1 expression was shown to be directly correlated with the stage of hepatic fibrosis." (PMID 39201329, 2024). "Similarly, increased TIMP-1 expression reduced liver fibrosis." (PMID 35745205, 2022). "In particular, it could reduce the content of TIMP-1 to the normal level, and the related research indicated that the decrease of TIMP-1 expression contributed to the degradation of liver fibrosis, so its mechanism may be related to decreasing the expression of TIMP-1." (PMID 33967794, 2021). "Moreover, immunostaining for the endogenous MMP inhibitor TIMP1, a marker of liver fibrosis, together with zymographic analysis of collagenase activity demonstrated that GS341 treatment promotes the disengagement of collagenase activity from TIMP1, while moving toward the fibrotic scar area." (PMID 32296422, 2020). "Similar to liver fibrosis, our study suggests that TIMP1 could be a marker for bladder fibrosis/RC." (PMID 33119677, 2020). "However, our study in TIMP-1-deficient mice did not confirm a functional role of TIMP-1 in the development of liver fibrosis or hepatocellular carcinoma." (PMID 28386095, 2017). "Progression of liver fibrosis is associated with decreased matrix degradation due to inhibition of matrix metalloproteases (mostly MMP-8 and MMP-13), which is the result of increased expression of their natural inhibitor TIMP-1, something observed in treated LX2 cells." (PMID 24637780, 2014). "Thus, targeting TNF-α and TIMP-1 may become a new therapeutic strategy for treating liver fibrosis and cholestatic liver injury." (PMID 23755201, 2013). "Thus, targeting TNF-α and TIMP-1 may become a new therapeutic strategy for treating liver fibrosis in cholestatic liver injury." (PMID 23755201, 2013). "As TIMP-1 has been described to have an antiapoptotic effect on activated HSCs, such a decrease in its production could be beneficial for the resolution of liver fibrosis." (PMID 22722906, 2013). "Moreover, MMP-2 appears to also have a protective role in mouse models of liver fibrosis by inhibiting collagen I synthesis and suppressing TIMP-1 upregulation which could thus contribute to lower fibrosis in MMP19KOs." (PMID 23056273, 2012). "In addition, administration of a TIMP-1 antibody attenuated CCl4-induced liver fibrosis, thus we hypothesized that deletion of TIMP-1 may reduce liver fibrosis after chronic CCl4 exposure." (PMID 21711826, 2011). "In the hepatic fibrosis model group, the MMP1/TIMP1 ratio was significantly decreased thus leading to reduced ECM degradation and increased collagen accumulation." (PMID 41293246, 2025). "Decreased the levels of liver fibrosis markers collagen (COL) 1, COL3, lysyl oxidas, tissue inhibitor of metalloproteinase 1 (TIMP1), α-smooth muscle actin, transforming growth factor β and hypoxia-inducible factor 1α." (PMID 40271056, 2025). "Enhanced liver fibrosis (ELF) scores for all three biomarkers (i.e. HA, PNIIIP and TIMP-1) exhibited a decreasing trend in the treated groups compared with that in the placebo group at baseline, week 4, week 8 and week 24 (available at Rheumatology online)." (PMID 40088930, 2025). "In human HBV-related liver fibrosis, genes such as COL1A1, TIMP1, ACTA2, and CTGF are consistently upregulated, reflecting structural reorganization and inflammatory signaling cascades." (PMID 41586310, 2025).
liver fibrosis (continued). "All these genes are involved in promoting fibrotic changes, especially GFAP, TIMP1, and THBS1, which are expressed by activated hepatic stellate cells, thereby driving liver fibrosis (38, –, 40)." (PMID 40793786, 2025). "This polarization has a direct pathological impact on induction the expression of collagen, tissue inhibitor of metalloproteinase 1(TIMP-1), and α-smooth muscle actin (α-SMA) which results in liver fibrosis." (PMID 40739075, 2025). "Exosomes from BMSCs with miR-148a-5p mitigated liver fibrosis in a mouse model by downregulating Smad4 in stellate cells, as confirmed by reduced TGF-β1 and tissue inhibitor of metalloproteinase 1 (TIMP-1)." (PMID 40676634, 2025). "In contrast to Foxo1M-KO, Foxo1/Notch1M-DKO augmented liver fibrosis, with concomitant increases in the mRNA expression of profibrotic genes, including αSMA, Col1α1, TGF-β1, CCL2, and TIMP1, in the liver after HFD feeding." (PMID 39122845, 2024). "In previous studies using murine models, the combined use of BCAAs attenuated liver fibrosis through inhibition of the TGF-β1 signaling pathway by downregulating several key pathway components, including SMAD-4, P-SMAD3L, TIMP-1, PDGFRβ, p-ERK, and COL1A2." (PMID 39495311, 2024). "Tissue inhibitor of metalloproteases 1 (TIMP-1) and procollagen III amino-peptide (PIIINP) are markers of fibrosis, notably contributing to the enhanced liver fibrosis score." (PMID 38956476, 2024). "In contrast, Col1A1, Timp1, and Tgfβ1 decreased, and Stat1 increased in both mRNA and protein levels following KIF18A overexpression in liver fibrosis models." (PMID 38372748, 2024). "The study showed that betaine modulates the antifibrogenic effects of MIF in TAA-induced liver fibrosis, by decreasing TGF-β1, PDGF-BB, MMP-2, MMP-9, TIMP-1, and the deposition of ECM (Coll1 and Coll3) in the liver." (PMID 38927544, 2024). "Compared with the WT mice, the Foxo1/YAPM-DKO mice exhibited significantly increased serum ALT levels, liver fibrosis, and mRNA levels of αSMA, Col1α1, TGF-β1, CCL2, and TIMP1 in the HFD-challenged livers." (PMID 39122845, 2024). "Corroborating the cardiac findings, in a model of nonalcoholic steatohepatitis, IL-11 inhibition by X203 or X209 decreased liver fibrosis by suppressing ERK activation and consequently MMP2 and TIMP1." (PMID 38392279, 2024). "Upregulation of TIMP-1 and TIMP-2, along with diminished MMP1 expression, have been reported in patients with progressive liver fibrosis." (PMID 39201329, 2024). "We performed real-time PCR for Tgfβ1, Tnfα, Colα1, Pdfgrs, Timp-1, CCND2, and Mycn, the key factors for NASH, liver fibrosis, and liver tumor in WT, the dKO, and the tKO mouse livers." (PMID 37586586, 2023). "Exogenous IL-10 was shown to reverse CCl4-induced hepatic fibrosis by reducing the production of TGF-β1, MMP-2, and TIMP-1 in a rat model, demonstrating that IL-10 has antifibrotic effects via inhibiting HSC activity." (PMID 36826975, 2023). "The role of increased expression of the Timp1 gene was revealed not only in the prevention of apoptosis of hepatic stellate cells (HSC), which play a key role in the development of liver fibrosis, but also its Act-dependent mitogenic effect on these cells." (PMID 36675165, 2023). "TGF-β1 can induce TIMP-1 expression after signaling to Smad3, while inhibiting MMP-1 expression, making the ratio of TIMP-1 to MMP-1 increase, and promoting liver fibrosis." (PMID 35529927, 2022). "This curcumin anti-hepatic fibrosis efficacy can be attributed to its inhibitory role through a direct binding to fibrosis-mediating proteins such as PDGFRB, Timp-1, TLR-9 and TGF-β." (PMID 36319750, 2022). "RT-PCR analyses supported these observations by showing that mRNAs of inflammatory mediators, IL-1β, IL-6, MCP-1, MCP-3 and TIMP-1 increased in CCl4- and BDL-induced liver fibrosis, and decreased in BI 113823-treated mice." (PMID 36514072, 2022).
liver fibrosis (continued). "Then, the effect of PC on liver fibrosis was further examined by identifying the characteristic indicators of liver fibrosis, including COL1A1, Lama1, and Timp1." (PMID 35721129, 2022). "Moreover, to further determine whether pre-ADSC treatment could significantly ameliorate liver fibrosis, we detected the expression of profibrogenic genes such as tissue inhibitor of metalloproteinases-1 (TIMP-1), matrix metalloproteinase (MMP-8 and 9), col1, and α-SMA." (PMID 35986406, 2022). "The ELF score includes three indices: tissue inhibitor of matrix metalloproteinases (TIMP1), the aminoterminal peptide of procollagen type III (PIIINP), and hyaluronic acid (HA), which mainly reflects the stroma deposition during liver fibrosis." (PMID 36186776, 2022). "The serum levels of resistin, TGF-β1, MMP-1, TIMP-1, collagen IA1 and PDGF-BB, which are markers that are known to be involved in the process of hepatic fibrosis, were assayed." (PMID 35715541, 2022). "Targeting activated HSCs in vivo decreased the expression of TIMP-1 and TIMP-2 and resulted in attenuated liver fibrosis." (PMID 36499616, 2022). "The Enhanced Liver Fibrosis (ELF) score is a serum marker panel consisting of three collagen metabolites, namely procollagen type III amino terminal propeptide (PIIINP), tissue inhibitor of metalloproteinases 1 (TIMP-1) and hyaluronic acid (HA)." (PMID 35177989, 2022). "Animal experiments have shown that quercetin can ameliorate liver fibrosis by inhibiting HSCs activation and ECM formation and regulating COL1A1, COL3A1, MMP9, and TIMP1 mRNA expression levels." (PMID 35791909, 2022). "RT-PCR and WB analyses indicated that liver fibrosis-related factors (including α-SMA, TGF-β1, TIMP-1, MMP-2, and Vimentin) were significantly downregulated, while E-cadherin was significantly upregulated in wild-type and αERKO mice after SSd treatment." (PMID 35694250, 2022). "The results showed that FA inhibited the proliferation and migration of LX2 cells and adjusted the expression of MMP-1, TIMP-1, COLI, α-SMA, TNF-α, IL-6 and IL-1β as well as promoted collagen metabolism to show potential in anti-hepatic fibrosis." (PMID 35035671, 2022). "In both AAV- TβR1 therapy groups and in the combination therapy group, the expression levels of collagen I, collagen III, MMP1, TIMP1, TGF-β1, and TβR1 in the liver of rats with CCl4-induced hepatic fibrosis were significantly lower than in the model group." (PMID 34181670, 2021). "The results showed that levo‐tetrahydropalmatine alleviated liver fibrosis by inhibiting the formation of extracellular matrix (ECM) and regulating the balance between TIMP1 and MMP2 in the two mice liver fibrosis models and cell model." (PMID 33438347, 2021). "Induction of liver fibrosis in rats using TAA for 6 weeks resulted in a significant elevation in hepatic contents of TGF-β1, α-SMA, collagen 1, and TIMP1 and reduced MMP9 content as compared to the normal group." (PMID 33628797, 2021). "Tissue inhibitor of metalloproteinase-1 (TIMP-1) has a specific inhibitory effect on MMP-1, which reduces the degradation of ECM by MMP-1 and leads to the development of liver fibrosis." (PMID 34611503, 2021). "Meta-analysis of the effects of angiotensin-converting enzyme inhibitors and angiotensin receptor blockers on patients with liver fibrosis showed a reduction in serum hepatic fibrosis markers such as TGF-β, TIMP-1, MMPs, and collagen." (PMID 34938271, 2021). "Hepatic mRNA levels of the fibrosis markers, Timp1 and Col1a1, revealed the protective effect of clodronate against MCD diet-induced liver fibrosis." (PMID 33664289, 2021). "We found that matrine, oxymatrine, sophocarpine, and oxysophocarpine partly suppressed the mRNA and protein liver fibrosis‐related genes TGF‐β1, COL1A, Fibronectin and TIMP1." (PMID 34323416, 2021).